RNY1P1 (RNY1 pseudogene 1)
Gene: Miscellaneous RNA gene on chromosome 13 (27,402,476 to 27,402,587, reverse strand). Ensembl gene ENSG00000201242.
Homologues: Orthologues: chimpanzee Y_RNA (94% identical), macaque Y_RNA (92% identical). Paralogues in human: RNY1P5 (85% identical), Y_RNA (84% identical), Y_RNA (83% identical), Y_RNA (82% identical), Y_RNA (81% identical), Y_RNA (80% identical), Y_RNA (79% identical), RNY1P11 (79% identical), RNY1 (78% identical), Y_RNA (78% identical), RNY1P4 (77% identical), Y_RNA (77% identical), and 92 more.